POSTN (periostin)
Diseases named in the same sentence as POSTN in open-access papers (continued):
Sharing a sentence is not in itself a finding about the gene and the disease.
inverted papilloma (1 paper, 2024). An endophytic benign papillary epithelial neoplasm that results from the invagination and proliferation of epithelial cells in the underlying stroma. "This study aimed to explore the expression of periostin in benign lesions of the nose and paranasal sinuses, focusing on a variety of different pathologies including mucoceles, inverted papillomas, choanopolyps, and cysts." (PMID 39728072, 2024). "Despite advances in understanding periostin’s role in inflammatory diseases, its function in benign nasal and paranasal lesions, such as inverted papillomas, mucoceles, choanopolyps, and retention cysts, remains unexplored." (PMID 39728072, 2024). "This study aims to evaluate the expression of periostin in mucoceles, inverted papillomas, choanopolyps and retention cysts." (PMID 39728072, 2024). "The expression of periostin was not significantly altered in inverted papillomas patients compared to controls, indicating a possible limited role of periostin in this condition’s pathogenesis." (PMID 39728072, 2024). "The expression profile of POSTN mRNA showed no statistically significant alteration in the inverted papillomas tissue samples compared to the control group." (PMID 39728072, 2024). "No statistically significant alterations were observed in POSTN serum levels or tissue protein levels, indicating that POSTN may not be involved in the pathogenesis or progression of inverted papillomas." (PMID 39728072, 2024).
ischemic disease (1 paper, 2015). Lack of blood supply to an area of the body, resulting in impairment of tissue oxygenation. "Our results suggest that periostin is a potential therapeutic candidate for treating ischemic disease with gene-based stem cell therapy." (PMID 26204963, 2015).
kidney injuries (1 paper, 2020). "Studies have shown that periostin is mainly produced by distal tubules, and the interstitial transformation tendency of distal tubules in various kidney injuries can be reflected by periostin." (PMID 33241962, 2020).
large cell lung carcinoma (1 paper, 2022). "In addition, POSTN expression was also higher in large cell lung carcinoma compared to healthy individuals." (PMID 35508298, 2022).
laryngeal carcinoma (1 paper, 2015). Carcinoma that arises from the laryngeal epithelium. "It noted up-regulation of S100A2, FGB, KRT17, FN1 and POSTN in laryngeal carcinoma tissues, as compared with normal tissue." (PMID 25874882, 2015). "Taken together, increased expression of POSTN may be a common event of tumor development in laryngeal cancer and can be used as a useful marker to predict the cancer’s malignancy." (PMID 25874882, 2015).
laryngeal squamous cell carcinoma (1 paper, 2024). A squamous cell carcinoma that arises from the larynx. "In laryngeal squamous cell carcinoma, HMGA2 expression was negatively related to the levels of miR-98, and the miR-98/HMGA2/periostin (miR-98/HMGA2/POSTN) axis played an important role in reversing EMT." (PMID 38361784, 2024).
leiomyoma (1 paper, 2019). A well-circumscribed benign smooth muscle neoplasm characterized by the presence of spindle cells with cigar-shaped nuclei, interlacing fascicles, and a whorled pattern. "They identified several proteins up regulated in the leiomyoma: POSTN, TNC, COL3A1, COL24A1, and ASPN." (PMID 31100862, 2019).
Lewis lung carcinoma (1 paper, 2022). "Exogenous addition of periostin increased polyomavirus middle T antigen and Lewis lung carcinoma cell proliferation in vitro, showing that periostin in sera of the TAC-operated mice plays key role in cancer cell proliferation." (PMID 35911555, 2022).
limb ischemia (1 paper, 2015). A ischemia that involves the limb. "In addition to the role of periostin in bone formation, intramuscular injection of recombinant periostin protein resulted in stimulation of angiogenesis and attenuation of severe limb loss in a murine model of limb ischemia." (PMID 25775460, 2015).
long bone fracture (1 paper, 2018). "In the long bone fracture group, periostin was reduced at 48 h (RGM 0.76, 0.71–0.83) and then progressively increased to a maximum at 8 weeks (RGM 1.15, 1.06–1.23) compared with the reference measurement." (PMID 30065761, 2018).
male infertility (1 paper, 2023). The inability of the male to effect fertilization of an ovum after a specified period of unprotected intercourse. "In addition, POSTN regulates spermatogonia proliferation through the Wnt/β-catenin signal pathway, which may serve as a cytokine for male infertility treatment." (PMID 36833370, 2023).
malignant glioma (1 paper, 2023). A grade III or grade IV glioma arising from the central nervous system. "The CLOCK-BMAL1 complex, which is a complex of two transcription factors, promotes angiogenesis in malignant gliomas by upregulating the extracellular matrix protein periostin (POSTN)." (PMID 38275375, 2023). "Regarding the promotion of angiogenesis in malignant gliomas, the CLOCK-BMAL1 complex was found to lead to transcriptional upregulation of periostin (POSTN), which promotes angiogenesis by activating TANK-binding kinase 1 (TBK1) in endothelial cells." (PMID 38275375, 2023).
meningioma (1 paper, 2024). A generally slow growing tumor attached to the dura mater. "Other proteins specifically associated with meningioma EVs include periostin, matrix glass protein, tendinin x, and tetrasin, all of which are usually linked to connective tissue and bone formation, implying that they could be useful in meningioma progression and invasion research." (PMID 38961907, 2024).
mesenchymal tumor (1 paper, 2014). "Subsequent microscopic examination and immunohistochemical analysis revealed a phosphaturic mesenchymal tumor mixed connective tissue variant (PMTMCT) showing a positive expression of somatostatin receptor 2A (SSTR2A), CD68, and Periostin." (PMID 25221676, 2014).
metastatic prostate carcinoma (1 paper, 2010). A carcinoma that arises from the prostate gland and has spread to other anatomic sites. "Whereas periostin expression was weak or absent in the stroma around normal prostate glands, strong periostin expression in tumour stroma was found in most primary and metastatic prostate cancers." (PMID 20534149, 2010).
mood disorder (1 paper, 2023). A cognitive disorder a disturbance in which the person's mood is hypothesized to be the main underlying feature. "The results further clarify the crucial role played by periostin in mood disorders, as well as the contribution of FKBPL and NOx levels to the stress response and gene expression control." (PMID 37375593, 2023). "This highlights the potential role of periostin in mood disorders." (PMID 37375593, 2023). "Despite the lack of research, there is evidence that periostin plays a role in mood disorders through its involvement in axon regeneration and neuronal plasticity in the cerebral cortex." (PMID 37375593, 2023).
myocardial diseases (1 paper, 2022). "Given the known role of periostin as a mediator in cell–matrix crosstalk and its association with fibroproliferative myocardial diseases, periostin has drawn widespread attention among researchers attempting to regulate cardiac remodeling after MI17,18,30." (PMID 36529756, 2022).
myopia (1 paper, 2020). "Before covering, no significantdifference was observed in the relative collagen I and periostin mRNA andprotein expression levels in the sclera of the guinea pig control andform-deprivation myopia groups (p>0.05)." (PMID 32049162, 2020).
nephronophthisis (1 paper, 2023). Progressive tubulointerstitial injury, inherited in an autosomal recessive pattern, caused by mutations in genes involved in ciliary function, which may result in an end stage renal failure. "As previously shown in vitro in human ADPKD cell and in vivo in the pcy murine model of nephronophthisis, we also observed an overexpression of periostin in epithelial cells lining the cysts in the jck murine model." (PMID 38039285, 2023). "Indeed, we observed a boost of MMP9 enzymatic activity in this model of nephronophthisis, and a ~40-fold increase of periostin mRNA by RT-qPCR." (PMID 38039285, 2023).
neurocutaneous syndrome (1 paper, 2018). A group of disorders characterized by ectodermal-based malformations and neoplastic growths in the skin, nervous system, and other organs. "However, the role of POSTN in neurocutaneous syndrome has never been described." (PMID 30574417, 2018).
neuroendocrine tumor (1 paper, 2021). "The transcriptomic landscape of 24,887 single cells was obtained and characterized as 10 cellular clusters, including epithelial, neuroendocrine tumor cells, T&NK cells, B cells, RGS5+ fibroblasts, POSTN+ fibroblasts, PDGFRA+ fibroblasts, endothelial, myeloid cells, and mast cells." (PMID 34185421, 2021).
oral diseases (1 paper, 2020). "The periostin immunomodulatory effects and associated biomarkers in context of oral diseases have been discussed." (PMID 32688410, 2020). "Additionally, periostin’s immunomodulatory effects and associated biomarkers in context of oral diseases have been discussed." (PMID 32688410, 2020).
oral lichen planus (1 paper, 2020). Oral lichen planus is a chronic inflammatory oral condition of unknown aetiology characterized by T-cell-mediated chronic immune response and abnormal epithelial keratinization cycle. "Other authors demonstrated that increased periostin expression in the oral mucosa and serum of patients with oral lichen planus (OLP) was associated with inflammatory response, where Th2 cytokine was predominant in immune imbalance and elevated TSLP concentrations." (PMID 33203095, 2020).
ossification (1 paper, 2025). The formation of bone or of a bony substance, or the conversion of fibrous tissue or of cartilage into bone or a bony substance. "This study demonstrates the role of M1 macrophages and their secreted POSTN in traumatic heterotopic ossification, highlighting the potential of POSTN as a therapeutic target for HO." (PMID 40823759, 2025).
Osteoblastoma (1 paper, 2018). A rare benign bone-forming neoplasm usually arising from the spine. "In osteoblastoma, newly formed osteoid stained strongly for periostin; staining for periostin was less pronounced in woven bone and was absent in lamellar bone surrounding the lesion." (PMID 30202513, 2018).
Osteopenia (1 paper, 2013). Osteopenia is a term to define bone density that is not normal but also not as low as osteoporosis. "We reappraised the efficacy and safety of Zoledronate (Zol) in ovariectomized (OVX) periostin (Postn)-deficient mice, a unique genetic model of systemic and jaw osteopenia." (PMID 23505553, 2013).
ovarian dysfunction (1 paper, 2024). The inability of the ovaries to function. "There is growing evidence suggesting a relationship between periostin levels, inflammation, and ovarian dysfunction." (PMID 39045965, 2024).
Parkinson disease (1 paper, 2023). A progressive degenerative disorder of the central nervous system characterized by loss of dopamine producing neurons in the substantia nigra and the presence of Lewy bodies in the substantia nigra and locus coeruleus. "While, the genes in POSTN low-expression group were enriched significantly in oxidative phosphorylation, Parkinsons disease, pentose phosphate pathway." (PMID 36611136, 2023).
parosteal osteosarcoma (1 paper, 2018). "In parosteal osteosarcoma, periostin expression was noted focally in the matrix in areas of tumor cell proliferation." (PMID 30202513, 2018).
peripheral artery occlusive disease (1 paper, 2017). "We previously reported that in vivo administration of both recombinant full-length protein and the first FAS I domain of periostin alleviated peripheral artery occlusive disease by stimulating the migration of humane endothelial colony forming cells (ECFCs) and subsequent angiogenesis." (PMID 29095886, 2017).
peripheral nerve tumors (1 paper, 2025). "We assessed POSTN and CTHRC1 expression in human patient-derived MPNST samples and a tissue microarray (TMA) composed of core biopsies from benign and malignant human peripheral nerve tumors." (PMID 39511408, 2025).
Peritoneal Fibrosis (1 paper, 2022). Disorder characterized by a wide range of structural changes in PERITONEUM, resulting from fibrogenic or inflammatory processes. "Intraperitoneal administration of a periostin aptamer significantly inhibited peritoneal fibrosis, and blunted profibrotic protein production and blood urea nitrogen level in diabetic mice." (PMID 35707463, 2022).
phyllodes tumor (1 paper, 2014). A benign, borderline, or malignant fibroepithelial neoplasm arising from the breast and rarely the prostate gland. "Decorin was expressed at reduced levels in phyllodes tumor tissues, whereas periostin was upregulated; this result was validated by immunohistochemical analysis of phyllodes tumors from 35 patients." (PMID 25400079, 2014). "In all three cases, decorin was expressed at higher levels in normal tissues than in phyllodes tumors, whereas periostin was upregulated in phyllodes tumor, as confirmed by immunoblot analysis." (PMID 25400079, 2014).
pneumococcal pneumonia (1 paper, 2016). A febrile disease caused by STREPTOCOCCUS PNEUMONIAE. "We identified ERM complex, PGLYRP1, PTPRC/CD45 and POSTN as new players in the pathogenesis of pneumococcal pneumonia." (PMID 27247105, 2016).
polyneuropathy (1 paper, 2022). A disease or disorder affecting more than one nerve. "In a model of polyneuropathy, and in injured nerve, periostin expression was also upregulated in SCs." (PMID 36134665, 2022).
polyposis (1 paper, 2021). "Along with that, in another female patient with atopic BA and AR who had polyposis-associated hypertrophy of the NM (with obstruction of the middle nasal passage on the left), the level of nasal periostin was significantly lower: 0.056 ng/mg." (PMID 34796003, 2021). "In patients with polyposis of the sinonasal mucosa, it was 0.17 [0.00; 0.32] ng/mg, i.e., close to the level of nasal periostin in patients without hypertrophy (0.18 [0.00; 4.30] ng/mg; p=0.83)." (PMID 34796003, 2021).
primary hypertension (1 paper, 2021). "The study aimed to evaluate serum periostin concentration as potential biomarker in pediatric patients with primary hypertension (PH)." (PMID 34063373, 2021). "The role of serum periostin as a biomarker of elevated blood pressure and arterial damage in pediatric patients with primary hypertension is yet to be unmasked." (PMID 34063373, 2021). "To conclude, the role of serum periostin as a biomarker of elevated blood pressure and arterial damage in pediatric patients with primary hypertension is yet to be unmasked." (PMID 34063373, 2021). "Our cross-sectional study analyzed periostin as a possible biomarker of blood pressure and subclinical arterial damage in pediatric patients with primary hypertension." (PMID 34063373, 2021).
psoriatic arthritis (1 paper, 2022). Joint inflammation associated with psoriasis. "Because Cretu’s study had two significant limitations: the researchers pooled samples (n = 5) before analyzing them by LC-MS/MS, and only two proteins, namely ITGB5 and POSTN, were validated by ELISA, other attempts to identify the biomarkers of psoriatic arthritis followed." (PMID 35327421, 2022).
retinal ischemia (1 paper, 2022). A ischemic disease that involves the retina. "Expression levels of isoforms 1, 2, and 5 are increased when the preretinal pathological neovascularization (NV) reaches the peak; they may be specific periostin splice variants for preretinal pathological NV in retinal ischemia." (PMID 36611844, 2022).
rhabdomyolysis (1 paper, 2022). Necrosis or disintegration of skeletal muscle often followed by myoglobinuria. "In conclusion, these findings indicate that periostin suppression might be a new therapeutic agent for acute renal injury caused by rhabdomyolysis." (PMID 36359784, 2022). "In the current study, we sought to define the impact of periostin for rhabdomyolysis-induced AKI." (PMID 36359784, 2022).
rheumatic diseases (1 paper, 2025). "Periostin regulates angiogenesis, inflammation, and fibrosis, key processes in the pathophysiology of rheumatic diseases (RDs)." (PMID 40053143, 2025).
sarcoidosis (1 paper, 2025). Sarcoidosis is a multisystemic disorder of unknown cause characterized by the formation of immune granulomas in involved organs. "Enhanced expression of collagens, periostin, and fibronectin have been extensively described in various forms of sarcoidosis." (PMID 40521183, 2025).
seminoma (1 paper, 2025). A radiosensitive malignant germ cell tumor found in the testis (especially undescended), and extragonadal sites (anterior mediastinum and pineal gland). "In the present retrospective study, 186 canine testicular tumours namely 61 Leydig cell tumours, 64 Sertoli cell tumours and 61 seminomas and 10 normal canine testicles were immunohistochemically tested for expression of POSTN, PDPN and Ki67 antigens." (PMID 41361308, 2025). "Normal testes were negative for both POSTN and PDPN, whereas 27 (44.3%) Leydig cell tumours, 54 (84.4%) Sertoli cell tumours and 56 (91.8%) seminomas were cytoplasmically positive for POSTN and 23 (37.7%), 49 (77.6%) and 44 (72.1%) were cytoplasmically positive for PDPN respectively." (PMID 41361308, 2025). "The intensity of POSTN and PDPN immunohistochemical reaction was stronger in Sertoli cell tumours and seminomas than in Leydig cell tumours." (PMID 41361308, 2025). "In addition, Ki67 antigen expression for both POSTN and PDPN correlated significantly with the number of positive cells and the intensity of the reaction in seminomas and Sertoli cell tumours." (PMID 41361308, 2025). "The results showed the absence of expression of POSTN and PDPN in normal canine testes and their expression in neoplastic ones, suggesting a role for these proteins in the carcinogenesis of the testis and encouraging further studies, in particular, on seminomas and Sertoli cell tumours." (PMID 41361308, 2025).
Sepsis (1 paper, 2022). Sepsis is defined as life-threatening organ dysfunction caused by a dysregulated host response to infection. "The compound also lowered the serum levels of YKL-40 and periostin in the oxidative lung injury induced by the experimental sepsis model." (PMID 36588685, 2022).
skin aging (1 paper, 2018). The gradual irreversible changes in structure of skin that occur as a result of the passage of time.. "POSTN has never been described in PYCR1-related ARCL, and our results indicate that POSTN may play an important role in skin aging, heart valves disease, and preglaucoma." (PMID 30574417, 2018). "Taken together, POSTN may play a crucial role in skin aging, heart valve disease, and preglaucoma." (PMID 30574417, 2018).
small cell lung carcinoma (1 paper, 2025). Small cell lung cancer (SCLC) is a highly aggressive malignant neoplasm, accounting for 10-15% of lung cancer cases, characterized byrapid growth, and early metastasis. "In this study, we present compelling evidence supporting the role of the secreted protein POSTN as an oncogene in the progression of small cell lung cancer (SCLC)." (PMID 39762921, 2025). "Taken together, these results demonstrate the pro-proliferative and pro-metastatic roles of POSTN in small cell lung cancer." (PMID 39762921, 2025).
spinal astrocytomas (1 paper, 2022). "Our study supports these findings and points to a potential role of periostin also in spinal astrocytomas." (PMID 35387112, 2022).
synovitis (1 paper, 2024). Inflammation of a synovial membrane. "This study demonstrates that IL-13 stimulation induces periostin production in hFLS, suggesting that IL-13 plays an important role in synovitis associated with KOA." (PMID 38711706, 2024). "Furthermore, periostin levels in the synovial fluid increased with KOA progression and may be a biomarker for estimating the severity of synovitis." (PMID 38711706, 2024).